MMP2 (matrix metallopeptidase 2)
Diseases named in the same sentence as MMP2 in open-access papers (continued):
Sharing a sentence is not in itself a finding about the gene and the disease.
hepatocellular carcinoma (225 papers, 2008 to 2025). A malignant tumor that arises from hepatocytes. "SHP-1 inhibits HOXA10 and TGFβ2 which in turn regulates the expression of the migration-associated proteins, MMP2/9, and the migration of hepatocellular carcinoma cells." (PMID 38644382, 2024). "The inhibitory effects of stellettin B on cell migration and invasion in human hepatoma cells are associated with downregulation of the activity and protein expressions of MMP-2 and MMP-9." (PMID 39057397, 2024). "In cancer, interleukins (ILs) induce neo-angiogenesis and enhance the activity of MMPs, which increases the metastatic activity as demonstrated in hepatocellular carcinoma where IL-8 and IL-17 cause MMP-2 and MMP-9 activation." (PMID 33981713, 2021). "The ability of miR-100 to attenuate lamellipodia formation, matrix metallopeptidase 2 (MMP2) activation and metastasis in hepatocellular carcinoma cells was associated to ICMT-RAC1 signaling inhibition." (PMID 33224889, 2020). "Using RNA-interference, a causal role of MMP2 in invasion had already been demonstrated in human retinal microvascular cells, in human extravillous trophoblast and in two hepatocellular carcinoma cell lines." (PMID 31783660, 2019). "The present results demonstrate that MFB has significant anti-invasion and anti-migration activities against SK-Hep-1 cells, a human hepatoma cell line, and that this effect is mainly associated with the induction of nm23-H1 expression and down-regulation of MMP-2 and MMP-9 activity." (PMID 27941649, 2016). "Moreover, decreased production of CXCR4 and MMP-2 in association with lower invasion of hepatocellular carcinoma cells could be related to the down-regulation of metastasis." (PMID 21909361, 2011). "MLX suppresses the migration, invasion, and colony-forming ability of hepatocellular carcinoma cells by regulating the expression of E-cadherin and MMP-2." (PMID 40649764, 2025). "The process by which MMP2 regulates the generation of sMICA is also affected by CD133 in hepatoma cells." (PMID 40563539, 2025). "For example, in hepatocellular carcinoma cells, TGFβ1 upregulates MMP2 via Smad3, boosting invasiveness." (PMID 40646747, 2025). "The conditioned medium of hepatocellular CAFs promoted VM formation and the expression of VM-related genes and proteins (MMP2 and EphA2) in hepatoma cell lines." (PMID 38459564, 2024). "Snail has been shown to stimulate MMP2 expression in human bone mesenchymal stem cells and hepatocellular cancer cells." (PMID 37143106, 2023). "The lncRNA DLX6-AS1 is up-regulated in human liver cells and tissues after interacting with miR-203a, promoting invasion in human hepatocellular carcinoma in an MMP2 MMP2-dependent manner." (PMID 37245177, 2023). "The administration of Polyphenon-B significantly reduced the incidence of DAB-induced hepatomas as evidenced by the modulation of MMP-2, MMP-9, tissue inhibitor of matrix metalloproteinase (TIMP)-2, and RECK as well as angiogenesis." (PMID 38139236, 2023). "Apart from the anti-CD 147 antibody strategy, researchers have demonstrated that small molecule (AC-73) inhibitors of CD147 dimerization can suppress MMP-2 production in hepatocellular carcinoma via the CD147-ERK-STAT 3-MMP-2 signaling pathway." (PMID 37090718, 2023). "It was also demonstrated that AITC and its N-acetylcysteine conjugate (a major metabolite of AITC) suppressed the proliferation of SK-Hep-1 human hepatoma cells by inhibiting invasion, migration and MMP-2/-9 activity." (PMID 36430307, 2022). "Exosome-transmitted circ_MMP2 enhances metastasis of hepatocellular carcinoma through inducing MMP2." (PMID 35342412, 2022). "Previous studies have shown that quercetin inhibits cell migration and invasion in various cancer cell types, including breast, osteosarcoma, hepatoma, and oral cancer cells, by inhibiting the expression levels and activities of MMP-2 and MMP-9." (PMID 35337161, 2022).
hepatocellular carcinoma (continued). "RA can inhibit the expression of Fyn in HepG2 hepatoma cells, as well as the proliferation, migration, and invasion of hepatoma cells, and the expression of matrix metalloproteinase-2 (MMP-2) and matrix metalloproteinase-9 (MMP-9) in a dose-dependent manner." (PMID 36278230, 2022). "Hepatocellular carcinoma cells secrete exosomes that deliver circ_MMP2 to human hepatocytes and hepatoma cells to increase matrix metalloproteinase 2 levels." (PMID 36275738, 2022). "For instance, exosomal circ_MMP2 accelerated the malignancy of hepatocellular carcinoma by modulating miR-136-5p/MMP2 axis." (PMID 34082824, 2021). "The highest levels of MMP-2 were secreted when primary HSCs were grown with hepatoma cells expressing HCV core, compared with HSCs grown alone or in the presence of “regular” hepatoma cells." (PMID 34065048, 2021). "Further study showed that miR-100/CXCR7 played a role in hepatocellular carcinoma progression by regulating metalloproteinase-2 (MMP2) and vascular endothelial growth factor (VEGF)." (PMID 34337085, 2021). "Most recently, overexpressed SMYD3 enhanced MMP2 and CDK2 expression in hepatocellular carcinoma and upregulated Bcl-2, Bcl-xl, MMP-2, and MMP-9 in NSCLC to facilitate tumorigenicity and cancer progression." (PMID 34201935, 2021). "The proteolytic enzymes; matrix metalloproteinase (MMP)-2 and -9 are highly expressed in hepatocellular carcinoma, which play important roles in HCC invasion by degrading the environmental extracellular matrix and the basement membrane." (PMID 32592368, 2020). "A doxycycline-treated group and a control group of engrafted human MHCC97H cells of hepatocellular carcinoma into BALB/c mice showed that doxycycline acted as an MMP-2 and MMP-9 inhibitor." (PMID 32377334, 2020). "Overexpression of UCK2 increased MMP2/9 expression and further activated Stat3 signaling, mediating the metastasis of hepatocellular carcinoma cells." (PMID 32894095, 2020). "Quercetin (MOL000098) has been reported to inhibit metastatic potential of human hepatocellular carcinomas by decreasing p-Akt, MMP-2, and MMP-9." (PMID 33381039, 2020). "In hepatocellular cancer, the transfection of the snake venom cystatin into tumoral cells has suppressed the tumor invasion and metastasis via suppressing MMP-2, MMP-9, and epithelial–mesenchymal transition." (PMID 33167431, 2020). "In 2016, Tang Y found that 14-3-3β Promotes Migration and Invasion of Human Hepatocellular Carcinoma Cells by Modulating Expression of MMP2 and MMP9 through PI3K/Akt/NF-κB Pathway." (PMID 31737636, 2019). "CLU increased MMP-2 expression in hepatocellular carcinoma cells, while CLU overexpression inhibited MMP-9 expression by reducing NF-κB activation in vascular smooth muscle cells." (PMID 31885575, 2019). "Beside the anti-CD147 antibody strategy, a small molecule (AC-73) inhibitor of CD147 dimerization has been shown to decrease MMP-2 production via CD147-ERK-STAT3-MMP-2 pathway in hepatocellular carcinoma." (PMID 31744072, 2019). "MMP-2 activity is the highest expressions in the tissue of hepatocellular carcinoma with metastasis and plays a key role in the degradation of the basement membrane and ECM, thereby enhancing migration of endothelial cells." (PMID 29356905, 2018). "Rosiglitazone, one of the thiazolidinediones, can inhibit metastasis in a murine model of hepatocellular carcinoma and inhibit pancreatic cancer cell invasion and metastasis by regulating MMP-2 expression through phosphatase and tensin homolog (PTEN)." (PMID 29316690, 2018). "This research indicates that serum MMP-9/MMP-2 ratio is a potential biomarker of hepatitis B virus-related hepatocellular carcinoma." (PMID 30262739, 2018). "The authors observed that serum MMP-9/MMP-2 ratios in hepatitis B virus-related hepatocellular carcinoma patients were significantly higher than those of other groups (healthy carriers, chronic hepatitis patients and cirrhosis patients)." (PMID 30262739, 2018).
hepatocellular carcinoma (continued). "A recent study found that 500 μM NaHS markedly increased MMP-2 expression in human PLC/PRF/5 hepatoma cells." (PMID 28698660, 2017). "Fibrosarcoma and hepatocellular carcinoma cells expressed both MMP-2 and MMP-9, glioblastoma cells MMP-2 and PMA-induced MMP-9, and uterine leimyosarcoma cells only PMA-induced MMP-9." (PMID 27618095, 2016). "In the present study, we used a MPP2 aCPP to deliver hTERT siRNA into SMMC-7721 hepatoma cells, known to overexpress MMP2, to silence the hTERT gene." (PMID 25671640, 2015). "Matrix metalloproteinase (MMP)-2 and -9 are proteolytic enzymes that are highly expressed in hepatocellular carcinoma." (PMID 26204832, 2015). "In the present study, we delivered human telomerase reverse transcriptase (hTERT) siRNA into SMMC-7721 hepatoma cells using a matrix metalloproteinase-2 (MMP2)-activatable cell-penetrating peptide (aCPP)." (PMID 25671640, 2015). "A low expression of miR-29b, often associated with poor-recurrence free survival in hepatocellular cancer (HCC), was experimentally found to be a direct target of MMP-2 with significant effects on angiogenesis and invasion." (PMID 24670365, 2014). "In our study, we found for the first time genipin is a specific inhibitor to MMP-2 activities in human hepatocellular carcinoma cells." (PMID 23029478, 2012). "Osteopontin, SDF-1α, and MMP-2 are important secreted molecules involved in the pathophysiology of human hepatocellular carcinoma (HCC)." (PMID 21909361, 2011). "We thus assessed the role of the SDF-1α/CXCR4 axis in the process of OPN mediated MMP-2 up-regulation in the two human hepatocellular carcinoma cell lines, HepG2 and SMMC7721." (PMID 21909361, 2011). "In a study by Zhao and co-workers on the hepatocellular carcinoma cell lines HepG2 and SK-Hep-1, Western blot analysis showed a significant reduction in MMP-2 and MMP-9 expression, resulting in strong anti-proliferative, anti-metastatic, and anti-invasive effects." (PMID 39335164, 2024). "A recent study reported that efficient knockdown of miR-21 by hierarchically tumor-activated nanoCRISPR-Cas13a (CHAIN) restored RECK expression and crippled downstream MMP-2, which undermined cancer proliferation, migration, and invasion in a hepatocellular carcinoma mouse model." (PMID 38612895, 2024). "Furthermore, heightened expression of TPX2 in HCC promotes cell proliferation and invasion through AKT signaling activation and upregulation of MMP2/9, underscoring its potential as a therapeutic target for hepatocellular carcinoma." (PMID 39100078, 2024). "Similarly, irradiation of hepatoma cells has been linked to the secretion of tumor necrosis factor-alpha (TNF-α), IL-6, VEGF, epidermal growth factor (EGF), MMP2, and MMP9, all of which enhance tumor invasion." (PMID 39759518, 2024). "Among them, MMP2 is the major MMP in the pathogenesis of EMT in hepatocellular carcinoma." (PMID 39544935, 2024). "In hepatocellular carcinoma cells, BK, via B2R, increases MMP2 secretion through the Src pathway." (PMID 39519260, 2024). "Furthermore, through the regulation of SOX4 by HAGLR, HOTAIR is activated and indirectly activates EZH2 and MMP2 (matrix metallopeptidase 2) to facilitate hepatocellular carcinoma metastasis." (PMID 37624034, 2023). "Hence, our finding reveals that macrophage-derived MMP-9 and MMP-2 are closely related to the rupture of the FC of hepatocellular carcinoma leading to tumor invasion." (PMID 36918768, 2023). "However, no previous study has investigated the correlation between MMP-9 and MMP-2 and FC rupture in hepatocellular carcinoma." (PMID 36918768, 2023). "A previous study revealed that bradykinin could upregulate the levels of TRPM7 and MMP2 to promote the invasion and migration of hepatocellular carcinoma cells." (PMID 34938313, 2021).
hepatocellular carcinoma (continued). "As we have shown in the previous sections, mortalin promoted the migration and invasion of hepatocellular carcinoma cells via RECK/STAT3 signaling, and Sal B inhibited EMT, the RECK/STAT3 pathway, MMP9/MMP2, and the migration and invasion of hepatocellular carcinoma cells." (PMID 34876128, 2021). "In addition, several studies reported the prognostic value of MMPs in cancer, such as MMP11 in PC, MMP2 in hepatocellular carcinoma, MMP1 in cervical squamous cell carcinoma, and so on." (PMID 33761734, 2021). "Hydroxysafflor yellow A could inhibit hepatocellular carcinoma through the inhibition of MMP-2, MMP-9, and p38MAPK signaling pathways in HepG2 cells." (PMID 32210799, 2020). "The fact that FAM83H-mediated increased the expression of snail and MMP2, and increased the invasiveness of hepatocellular carcinoma cells suggests that FAM83H might be involved in the epithelial-to-mesenchymal transition of cancer cells." (PMID 30723706, 2019). "In hepatocellular carcinoma (HCC), vascular channels were formed, and these vessels were associated with RhoC FAK/Paxillin signaling regulation as well as with high expression of RhoC/ROCK2, VE-cadherin, and MMP2 mediated by ERK/MMPs signaling." (PMID 31993365, 2019). "MMP-2 protein expressions are high level in hepatoma cells, such as SK-Hep1 cells." (PMID 29356905, 2018). "Our data showed that the CPP and its cargo (hTERT siRNA) successfully entered hepatoma cells, which could have only happened after cleavage of the linker by MMP2." (PMID 25671640, 2015). "In conclusion, our study demonstrates that miR-324-5p suppresses hepatocellular carcinoma cell invasion by attenuate the expression and activity of MMP2 and MMP9, subsequently counteracting ECM degradation, through post-transcriptionally downregulating ETS1 and SP1." (PMID 26177288, 2015). "So far, it is known that KLF4 acts as a tumor suppressor by positively regulating the levels of E-cadherin in hepatocellular carcinoma, MMP-2 and MMP-9 metalloproteases in neuroblastoma and the TF Slug during the epithelial to mesenchymal transition of mammary epithelial cells." (PMID 25181544, 2014). "Abnormal expression of MMPs is believed to play an important role in tumor cell invasion and metastasis in human cancers, including hepatocellular carcinoma.Among the MMPs, the roles of MMP-2 and MMP-9 in the invasiveness and metastasis of cancer cells are well characterized." (PMID 22546345, 2012). "Similarly, in hepatocellular carcinoma cells, claudin-10 expression promoted cell survival, motility, and invasiveness, while matrix metalloproteinase 2 (MMP2) was up-regulated." (PMID 21789222, 2011). "The observation that rhOPN induced SDF-1α, CXCR4 and MMP-2 expression in human hepatocellular carcinoma cells suggested that the SDF-1α/CXCR4 axis might play a role in osteopontin-dependent tumor progression." (PMID 21909361, 2011). "In comparison with untreated cells, recombinant human osteopontin (rhOPN) up-regulated CXCR4, SDF-1α, and MMP-2 expression about 5-, 4-, and 6-fold on the protein levels through binding to integrin αvβ3 and CD44v6 in hepatocellular carcinoma cells (SMMC7721 and HepG2)." (PMID 21909361, 2011). "Serum MMP-9 and MMP-2 cutoff values can effectively predict whether FC is ruptured in patients with hepatocellular carcinoma pre-operatively, determine the range of surgery, and provide a new diagnostic method for clinical therapy, which is of guiding significance." (PMID 36918768, 2023). "In hepatocellular carcinoma and cervical cancer, it has been demonstrated that Icariside II could weaken the migratory and invasive ability of HuH-7, HepG2, and HeLa cells through inhibiting metastasis-related protein MMP2/9 expression." (PMID 33981241, 2021).
hepatocellular carcinoma (continued). "Additionally, this research found that MMP-9/MMP-2 ratios in advanced, inoperable hepatitis B virus-related hepatocellular carcinoma patients were significantly higher than those in early-stage hepatitis B virus-related hepatocellular carcinoma patients." (PMID 30262739, 2018). "In particular, miR-29b expression enhances the survival of patients with hepatocellular carcinoma (HCC) by repressing matrix metalloproteinase 2 (MMP-2) expression and activity." (PMID 26155940, 2015). "MiR-29b can suppress tumor angiogenesis, invasion and metastasis by regulating MMP-2 expression in hepatocellular carcinoma (HCC)." (PMID 22943456, 2012). "To determine whether the reduced activity of MMP-2 is attributable to the suppression of protein expression in hepatocellular carcinoma cells, we detected the mRNA transcripts and protein levels of MMP-2/9 in HepG2 and MHCC97L cells with semi-quantitative PCR and western blot, respectively." (PMID 23029478, 2012). "For instance, hepatoma cells induced into senescence by therapy secrete large amounts of proteases, such as MMP-2 (matrix metalloproteinase-2), which degrade the surrounding extracellular matrix." (PMID 41516233, 2025). "HRH1 overexpression in hepatocellular carcinoma (HCC) was shown to promote tumor metastasis by inducing matrix metalloproteinase (MMP)-2, and treatment with HRH1 antagonists was reported to decrease the HCC risk in patients with hepatitis B virus (HBV), HCV, or dual infection." (PMID 40113769, 2025). "Another study reported that HSCs can mediate hepatoma progression by releasing factors that promote epithelial-mesenchymal trans-formation and angiogenesis, such as VEGF, MMP2, MMP9, bFGF, and TGF-β." (PMID 39742261, 2024). "More recently, bradykinin has been demonstrated to promote the migration and invasion of human hepatocellular carcinoma cells by upregulating the expression of TRPM7 and facilitating the secretion of matrix metalloproteinase 2 (MMP2)." (PMID 38255793, 2024). "SHP-1 can inhibit the expression of MMP-2 and MMP-9 protein in hepatocellular carcinoma cells related to migration.." (PMID 38644382, 2024). "The silencing of ACKR3 also leads to decreased matrix metalloproteinase-2 (MMP2) and vascular endothelial growth factor (VEGF) expression, inhibiting migration and invasion of tumor endothelial cells in hepatocellular carcinoma." (PMID 38920657, 2024). "Activated CAFs further promote cancer progression by secreting angiogenic cytokines, including VEGF, MMP2, MMP9, b-FGF, and TGF-β, and enhance EMT progression in hepatoma cells." (PMID 38584703, 2024). "SHMT1 affects the expression of downstream molecules ROS through NOX1 in hepatocellular carcinoma, leading to the production of EMT and MMP2 and ultimately influencing its proliferation." (PMID 38594513, 2024). "In conclusion, MMP-9 and MMP-2 were able to effectively differentiate between ruptured FC and intact FC, both on the tissue level and on the serum level, suggesting that it has great potential in diagnosing whether FC is ruptured in patients with hepatocellular carcinoma." (PMID 36918768, 2023). "Snail, a zinc finger transcription factor, increases cancer invasion by upregulating members of the MMP family, such as MMP-1, MMP-2, and MMP-7, in hepatocellular carcinoma." (PMID 36522523, 2023). "In human hepatocellular carcinoma (HCC), chelerythrine can inhibit human hepatocellular carcinoma Hep3B cells by downregulating the expression of p-FAK and MMP-2/9." (PMID 37764364, 2023). "Treatment with baicalein reduced the production of matrix metalloproteinase-2 (MMP-2), matrix metalloproteinase-9, and urokinase-type plasminogen activator (u-PA), as well as proteinase activity, in hepatocellular carcinoma MHCC97H cells." (PMID 36080453, 2022).